TNF (tumor necrosis factor)
Diseases named in the same sentence as TNF in open-access papers (continued):
Sharing a sentence is not in itself a finding about the gene and the disease.
Sepsis (continued). "Several cytokines associated with sepsis, such as TNF‐α and IFN‐γ, are increased with LPS/PepG treatment." (PMID 37021779, 2023). "A study has illustrated that elevated levels of naturally occurring inflammatory mediators, such as nitrous oxide and TNF-α, are linked to the progression of severe sepsis, shock, or even mortality." (PMID 38138157, 2023). "Some cytokines associated with inflammation, such as IL‐1β, TNF‐α, and IL‐10, have been found to play essential roles in the occurrence and development of sepsis." (PMID 37382273, 2023). "M3 was also protective in mice with CLP-sepsis, measured by decreased levels of serum AST, ALT, TNF-α and IL-6, and attenuated severity of sepsis-associated acute lung injury." (PMID 35784361, 2022). "Anti-inflammatory drugs, including steroids and anti-IL-6 receptor (IL-6R) or anti-TNFα antibodies can reduce tissue harm but augment the risk of sepsis." (PMID 35937253, 2022). "Second, quantification of circulating TNF in natural sepsis revealed concentrations inadequate to cause organ damage or death." (PMID 35814227, 2022). "An increase in the level of TNF-α in the serum of patients with sepsis increases the risk of mortality; moreover, the level of IL-6 in the serum of patients with sepsis decreases, which helps patients with sepsis recover from the illness." (PMID 35370629, 2022). "For example, a systematic review and meta-analysis demonstrated that TCM treatment was associated with lower levels of IL-6 and TNF-α among sepsis patients." (PMID 35722155, 2022). "COPS2 is an important component of the COP9 signalosome complex, which contributes to various cellular processes, the regulation of the ubiquitin conjugation pathway, and also development of sepsis in patients with TNF-α rs1800629 A variant." (PMID 35041720, 2022). "LPS-induced sepsis can cause the body to produce many inflammatory mediators (IL-1, IL-6, and TNF-α), resulting in a cascade of inflammatory responses that can cause extensive tissue and cell damage and damage to multiple organ structures." (PMID 35482440, 2022). "TNF-α and IL-1β following sepsis have also been considered as the critical factors causing cognitive impairment." (PMID 36552192, 2022). "ROC curve analysis revealed that the diagnostic value of plasma WBC, CRP, and TNF-α for sepsis was dissatisfactory, while PCT and IL-6 were slightly better." (PMID 36402943, 2022). "In LPS-induced sepsis, the expression of pro-inflammatory markers, such as IL-6 and TNF-α, is associated with the degradation of the vascular endothelium glycocalyx." (PMID 35200650, 2022). "We found that the serum concentration of IL-6 and TNF-α, two pro-inflammatory cytokines regularly associated with sepsis, differed between both groups of mice only after the re-emergence of bacteria from the spleen." (PMID 35720383, 2022). "Substantial IL-1β, IL-6, TNF-α, and cell fragments cause renal tubular epithelial cell damage in sepsis-induced AKI." (PMID 35165294, 2022). "When sepsis occurs, inflammatory cells in the body are activated, which can release a large number of inflammatory mediators, such as tumor necrosis factor, interleukin 1, and oxygen free radicals, causing serious damage to the tissues and organs of the body." (PMID 35186224, 2022). "In sepsis, inflammatory cells are activated and release a large number of inflammatory mediators, such as tumor necrosis factor (TNF), interleukin-1, and oxygen free radicals, which cause serious damage to the tissues and body organs." (PMID 35720321, 2022). "TNF-α is associated with the severity of sepsis and is the primary mediator in the development of sepsis." (PMID 35959169, 2022). "Inflammation can increase peroxide levels via driving such oxidative stress, and while tissue damage severity in the context of sepsis is correlated with TNF-α levels, it is also linked to oxidative damage." (PMID 35978995, 2022).
Sepsis (continued). "CLP sepsis caused increased expression of the pro-inflammatory cytokines TNF-α, IL-1β, IL-6, as expected." (PMID 35625756, 2022). "Recent studies have shown that IL-3 plays an essential role during early sepsis: IL-3 operates upstream of key CKs [e.g., IL-6, IL-1β, and tumor necrosis factor–α (TNF-α)], and high IL-3 levels increase the risk of CK storms." (PMID 36129990, 2022). "MTA is an increasingly appreciated metabolic regulator of susceptibility and severity in sepsis; high plasma levels correlate strongly and positively with IL-6 and IL-8, and weakly with TNF-α, and signal a worse prognosis due to hyperinflammation." (PMID 35202243, 2022). "Based on previous research, TNF-α rs3615225 has been associated with gastric cancer and sepsis risk, particularly in eastern populations." (PMID 35888018, 2022). "In sepsis, a correlation between low HLA‐DR expression and impaired TNF production in septic monocytes upon LPS stimulation has been demonstrated, and this endotoxin tolerance has been suggested to be associated with sepsis severity." (PMID 35285058, 2022). "Herein, we found that AE was able to alleviate associated changes in spleen index and suppress LPS-induced TNF-α, and IL-6 production, suggesting that it plays an important protective role as an anti-inflammatory agent in our murine sepsis model." (PMID 35978995, 2022). "Even if circulating sTNFR act by binding TNF-α and by decreasing the number of receptor on the cellular membrane, the elevation of circulating levels has been associated with mortality during sepsis and with development of AKI in septic shock." (PMID 36287942, 2022). "Significant differences in TNF-α and G-CSF between hypernatremia patients and other groups are evidence that hypernatremia is associated with inflammation in sepsis." (PMID 36140385, 2022). "Plasma concentrations of specific cytokines TNF-α, IL-1β, IL-6, and IL-8 are often elevated in patients with sepsis, and cytokine concentrations are associated with the severity and prognosis of sepsis." (PMID 36199375, 2022). "For example, this protease was found to be involved in the degradation of MC-derived TNF-α in a murine model of sepsis, as MCPT-4-deficient mice exhibited increased levels of intraperitoneal TNF-α and higher numbers of peritoneal neutrophils." (PMID 35251027, 2022). "The up-regulation of TNF-α, IL-1β, and IL-6 has been confirmed to be inextricably associated with sepsis-elicited myocardial damage." (PMID 35599576, 2022). "The production of IL-6, TNFα, IL-18, and IL-1 pro-inflammatory cytokines along with IL-10 (anti-inflammatory cytokine) is a hallmark response to sepsis." (PMID 36439175, 2022). "By doing real time PCR, we observed sepsis caused increase in TNFα mRNA in brain 6 h after induction, and cit-AuNP treatment performed 2 h after induction of sepsis reduced TNF mRNA levels in the cerebral tissue." (PMID 33608025, 2021). "Sepsis was independently associated with higher serum IL-18 and TNF levels in two time-point GEE models (53–723, p = 0.023 and 0.3–64, p = 0.048, respectively)." (PMID 35054259, 2021). "They demonstrated that IL-1β, TNF-α and IL-6 enhance bacterial growth in patients with sepsis-associated ARDS." (PMID 34945111, 2021). "Previous studies on myocardial dysfunction during sepsis underlined the role played by the cytokine storm, especially by TNF-α and IL-1β in inducing a precocious decrease in myocardial contractility." (PMID 34696451, 2021). "Serum inflammatory mediators associated with sepsis (IL-18, IL-18BP, TNF) were determined and correlated with the outcome of SBT." (PMID 35054259, 2021). "Excessive production of pro-inflammatory cytokines like (TNF-α, IL-1β, and IL-6), chemokines, and other inflammatory molecules are associated with sepsis." (PMID 35005242, 2021).
Sepsis (continued). "Although we did not observe a significant increase of cytokines at the end of SBT, we demonstrated that sepsis was independently associated with higher serum IL-18 and TNF levels at two time points (baseline, 30 min)." (PMID 35054259, 2021). "Compared with low TNF-α, the risk of sepsis in patients with high TNF-α levels was 7.205 (95%CI = 3.420–15.177, p < 0.05), and the adjusted OR was 1.624 (95%CI = 0.531–4.970, p > 0.05)." (PMID 34745113, 2021). "Sepsis caused a significant increase in the expression of TNF-α level in testicular tissue in the sepsis group compared with the sham group (1.53 ± 0.02 vs 0.63 ± 0.03 %, P<0.05)." (PMID 35317115, 2021). "The NF-κB pathway has been reported to be a critical signaling pathway involved in the inflammatory response in sepsis, and cytokines, such as IL-1β and TNF-α, are associated with the activation of NF-κB." (PMID 34820388, 2021). "TNF-α provokes several inflammatory diseases, including cachexia, cytotoxicity, and sepsis, and IL-1β is believed to be associated in LPS-stimulated inflammatory processes." (PMID 35008520, 2021). "The results showed that sepsis caused increased expression of TNF-α in blood, which was distinctly reduced by PMVs administration as compared to SMVs group." (PMID 34784912, 2021). "The reduced pathology of sepsis-caused ALI was correlated with reduced levels of pro-inflammation cytokines such as TNF-α, IL-6 and IL-1β in blood and their mRNA transcriptional level directly in lung tissue." (PMID 33842398, 2021). "The aim of this study was to investigate the association between disease severity in patients with sepsis and TNF-α, B cell lymphoma-extra-large (BCL-xL), and serum Mitochondrial membrane potential (MMP)." (PMID 34193088, 2021). "A significant correlation has been encountered between the development of severe sepsis and the genotypes of the same investigated SNP in this study, TNF-α (–376 G/A), but the risk for AKI was the focus." (PMID 34692772, 2021). "Compared to the group with the lowest TNF-α levels (Q1), the ORs of sepsis risk in the Q2, Q3, and Q4 groups were 2.087 (0.707–6.165), 5.333 (1.839–15.471), and 31.000 (8.195–117.272), respectively." (PMID 34745113, 2021). "Subsequently, excessive expression of TLR4 caused over-activation of NF-κB and increased release of inflammatory mediators such as TNF-α, IL-6, and IL-8, which can cause tissue injury and even sepsis." (PMID 34712822, 2021). "TNF-α, secreted in the early stage of sepsis and closely linked with cardiac systolic and diastolic impairment, induces the production of inducible NO synthase and the following NO elevation, which further leads to vasodilation and inflammation in sepsis." (PMID 33645622, 2021). "The results of this study showed that gut-origin sepsis was associated with increased expression of the proinflammatory cytokines (TNF-α, IL-1β, IL-6, and HMGB1) and decreased expression of anti-inflammatory cytokine IL-10." (PMID 34790828, 2021). "While both asphyxia and sepsis cause increased plasma level of IL-6 concentration, TNF-α level is more associated with sepsis." (PMID 34282369, 2021). "The BCAAs are primarily catabolized in skeletal muscle and increased rates of BCAA oxidation have been observed in a range of conditions associated with cachexia, including sepsis, trauma, and treatment with endotoxin or tumor necrosis factor (TNF)." (PMID 34621740, 2021). "In other studies, elevated TNF-a concentrations were associated with a worse prognosis in patients with sepsis." (PMID 33917002, 2021). "Some studies have shown that indicators such as tumor necrosis factor-α (TNF-α), interleukin-6 (IL-6), and interleukin-10 (IL-10) are used as early biomarkers of sepsis-associated ARDS." (PMID 34095029, 2021). "In particular, multiple inflammatory cytokines, including ILs, TNF-α and interferons, are implicated in the development of sepsis." (PMID 34276358, 2021).
Sepsis (continued). "In this ancillary analysis of the REALISM dataset, we showed that both decreased mHLA-DR and TNF-α release were associated with a higher risk of death or nosocomial infections in critically ill patients with sepsis, trauma or after elective surgery." (PMID 35011836, 2021). "A similar vulnerability ratio has been observed in male rodents, which are more susceptible to LPS-induced sepsis and show higher levels of TNF compared to female animals." (PMID 33803476, 2021). "In zebrafish with sepsis due to inoculation with S. pneumoniae with the morpholino directed against HIVEP1 was associated with increased mRNA expression of TNF-α, IL-1β, CXCL8a and CXCL8b, as well as enhanced mortality." (PMID 34804025, 2021). "IL-6 and TNF-α are the critical mediators of sepsis, and their uncontrolled regulation can cause cell death and DNA damage depending on the severity of cytokine production." (PMID 34194518, 2021). "The purpose of this study was to concomitantly evaluate the association between mHLA-DR and TNF-α release and adverse clinical outcome (i.e., death or secondary infection) after severe trauma, sepsis or surgery in a cohort of 353 ICU patients." (PMID 35011836, 2021). "Studies have implicated that overproduction of IL-1β, IL-6, TNF-α, and IL-10 in mice and humans is associated with sepsis, and IFN-γ expression is enhanced persistently in patients who die of sepsis." (PMID 34612675, 2021). "Sepsis was independently associated with higher serum levels of IL-18 and TNF at two time points (before and at the end of SBT)." (PMID 35054259, 2021). "Our study shows that genetic variation in the first intron of the TNF-α gene to have an important impact on the susceptibility to sepsis and its severity." (PMID 32171247, 2020). "Fifteen [47%] of the 32 patients with anastomosis-related sepsis had documentation of at least one of the risk factors of ongoing steroid therapy, anti-TNF therapy, intra-abdominal abscess, or significant preoperative weight loss." (PMID 32215559, 2020). "Sepsis-associated inflammatory cytokines, including IL-6, TNF-α, and IL-10, were significantly elevated in antibiotic-treated Rag2γc mice 12 days post infection compared to their levels in the B6 mice (p < 0.001)." (PMID 33488563, 2020). "Beyond activating the endothelium and leukocytes, TNF-α, IL-1β, and IL-6 combine to induce the systemic acute phase response that is implicated in the development of sepsis." (PMID 32849612, 2020). "The cytokine tumor necrosis factor (TNF) is generally thought to play a pivotal role in the pathogenesis of sepsis and ARDS, which is frequently caused by sepsis." (PMID 32410851, 2020). "In sepsis condition, Zn deficiency resulted in increased NF-κB p65 mRNA expression resulting in upregulation of target genes interleukin (IL)-1β, TNFα, and ICAM-1 and increase in proinflammatory cytokines IL-6, IL-8, and TNF." (PMID 33193427, 2020). "In an ALI rat model caused by cecal ligation and puncture-induced sepsis, two independent laboratories demonstrated that the protein levels of TNF-α and IL-6 in BALF measured by ELISA were highest at 6 h and declined at later time points (12 and 24 h)." (PMID 32024527, 2020). "When mice were administered either compound 1 or 2 in saline (1% Tween 20) before LPS injection (i.p.)to cause sepsis, the levels of TNF-α in the blood were diminished markedly relative to those of TNF-α in the blood of sham-treated mice." (PMID 32823787, 2020). "Elevated IL-10 levels and a high IL-10/TNF-α ratio have been associated with mortality in severe sepsis patients, and similar findings have been previously reported among SAB patients." (PMID 33256638, 2020). "According to those authors lipopolysaccharide and tumor necrosis factor-α, as the main causes of sepsis, provoked decreased fructose absorption in the jejunum." (PMID 32610537, 2020).
Sepsis (continued). "This SNP, namely TNF-α +489G/A was associated with a diminished risk of sepsis under the dominant model (GA + AA vs GG, OR = 0.53; 95% CI = 0.34–0.82, p = 0.004) and allelic comparison (A vs G, OR = 0.54; 95% CI = 0.38–0.79, p = 0.001)." (PMID 32171247, 2020). "Many pro-inflammatory cytokines, such as TNF-α and IL-6, reportedly triggered in sepsis, which caused an overwhelming immune response against the infection." (PMID 32625095, 2020). "Blood gas analysis showed that all TNF-treated mice suffered from severe metabolic acidosis with a pH < 7.2, indicating that TNF had caused sepsis-like symptoms." (PMID 32410851, 2020). "TNF-α inhibitor manifested excellent anti-inflammatory and antioxidant effects in Listeria monocytogenes induced fatal septicemia-associated ALF." (PMID 34138224, 2020). "For septicemia caused by V. vulnificus, such cytokines include tumor necrosis factor alpha (TNF-α), interleukin 1 beta (IL-1β), IL-6, and IL-8." (PMID 32380667, 2020). "That said, CD8+ T cell exhaustion remains a hallmark of sepsis, as evidenced by the recently reported decrease in the synthesis of IL-2 and TNFα by CD8+ T cells." (PMID 33613540, 2020). "We included in the haplotype analysis polymorphisms located in the promoter of the TNF-α gene, namely -308G/A, -238G/A and -376G/A and we investigated if haplotypes are associated with sepsis." (PMID 32171247, 2020). "Considering the crucial role of acute inflammatory responses in the development of sepsis patients, we further evaluated the association of serum miR-19b-3p level with the release of inflammatory factors, including IL-6 and TNF-α." (PMID 32188465, 2020). "We found that lnc‐MALAT1/miR‐125a axis was positively associated with APACHE II score, SOFA score, Scr, CRP, TNF‐α, IL‐1β, IL‐6, and IL‐8, while negatively associated with albumin in sepsis patients." (PMID 32309886, 2020). "In the current study, miR-19b-3p level was determined to be negatively associated with serum levels of both IL-6 and TNF-α in sepsis patients." (PMID 32188465, 2020). "Higher TNF-α gene expression also increased the risk for sepsis, infection and NEC in a neonatal rat model." (PMID 32443898, 2020). "IL-6, TNF-α, IL-1β, and IL-12 are hallmark inflammatory mediators of sepsis that constitute the cytokine storm." (PMID 32153410, 2020). "Splenomegaly in severe sepsis survivors was associated with the expansion of splenic leukocytes, among which Ly-6Chigh monocytes strongly upregulated tumor necrosis factor in response to inflammatory stimuli." (PMID 33197883, 2020). "In particular, we aimed to determine if single nucleotide polymorphisms (SNPs) of TNF-α gene are associated with sepsis in terms of risk, severity and outcome." (PMID 32171247, 2020). "We reconfirm that circulating TNF-α levels are significantly increased in deceased versus survivors, as well as in septic shock patients compared to sepsis, this difference being determined by the WT G allele of the studied SNPs." (PMID 32171247, 2020). "This is in line with other studies that did not identify an association between the G/A genotypes of the TNF-α -308 and/or -238 SNPs and sepsis risk in ICU Caucasian patients." (PMID 32171247, 2020). "Several SNPs in the promoter of TNF-α gene have been previously linked to sepsis risk, including -308G/A, -376G/A and -238G/A." (PMID 32171247, 2020). "Excessive inflammatory response is associated with multiple organ failure and poor outcome in sepsis, and is characterized by enhanced expression of inflammatory factors including IL-1β, IL-6, and TNF-α." (PMID 33324396, 2020). "It has been shown that higher IL-6 and TNF-α levels are associated with a higher risk of developing sepsis, and that, among patients with sepsis, men had worse outcomes, higher TNFα, and lower IL-10 levels than women." (PMID 32485823, 2020).